FANCM (FA complementation group M)
Diseases named in the same sentence as FANCM in open-access papers (continued):
Sharing a sentence is not in itself a finding about the gene and the disease.
breast cancer (51 papers, 2012 to 2025). A primary or metastatic malignant neoplasm involving the breast. "Altogether, the combined prevalence of the studied high and moderate-risk variants in the unselected breast cancer cohort was 7.1% (165/2336), and 8.9% (208/2334) when including the FANCM variants (c.5101C > T and c.5791C > T with OR < 1)." (PMID 40009290, 2025). "Altogether, the overall prevalence of the moderate-to-high risk recurrent DDR gene variants in the unselected breast cancer cohort was 7.1% (8.9% when including the FANCM variants)." (PMID 40009290, 2025). "Compared to other FANCM variants studied, milder patient phenotypes and only late onset breast cancer have been reported for the homozygous C‐terminal c.5101C>T variant, which is enriched in Finland." (PMID 40832744, 2025). "One BRCA2 variant carrier reported a second‐degree family history for cervical cancer and potential ovarian cancer, and one FANCM variant carrier reported a second‐degree family history of breast cancer." (PMID 39440754, 2025). "The distinct biochemical signatures of patient mutations - ATPase-dead variants causing infertility versus MM1 mutations in breast cancer - reflect FANCM’s separable functions." (PMID 40447800, 2025). "Homozygous or compound heterozygous FANCM loss-of-function variants have previously been reported to increase the breast cancer risk, and cause hypersensitivity to chemotherapy and radiation treatments due to acute toxicity." (PMID 40009290, 2025). "A recent study has proposed the existence of potential genetic modifiers in the Finnish population, considering the breast cancer risk associated with the heterozygous FANCM c.5101C>T variant." (PMID 40832744, 2025). "Here, the authors analyse pathogenic variants associated with breast cancer susceptibility in Hispanic/Latina women using genomics, and find that loss of function variants in FANCM are strongly associated with ER-negative breast cancer risk." (PMID 40841357, 2025). "For instance, biallelic mutations in FANCM exhibit chromosomal fragility and increase the risk of breast cancer and chemotherapy toxicity." (PMID 38745917, 2024). "In this study, we re-analysed the BRIDGES FANCM sequencing data assessing the breast cancer risk effects of 689 unique MVs in 39,885 European breast cancer cases and 35,271 controls from population- and family-based studies." (PMID 36707629, 2023). "The meta-analysis indicated that FANCM MVs overall are associated with breast cancer risk (OR = 1.22; 95% CI 1.08–1.38; P = 0.002)." (PMID 36707629, 2023). "Overall, our results showed that perturbation of the FANCM gene has an impact on breast cancer risk, reinforcing the knowledge that FANCM is a breast cancer gene predisposing especially to develop ER-negative and TNBC disease subtypes." (PMID 36707629, 2023). "To date, the potential association between FANCM MVs and breast cancer risk has been investigated by three studies in which all the rare variants were combined in burden analyses." (PMID 36707629, 2023). "Overall, our results and those from the previously conducted studies, indicate that FANCM MVs are associated with familial breast cancer risk, suggesting that these variants are low-risk susceptibility variants for breast cancer." (PMID 36707629, 2023). "In this study, we further used the BRIDGES study to test 689 FANCM MVs for association with breast cancer risk, overall and in ER-negative and TNBC subtypes, in 39,885 cases (7566 selected for family history) and 35,271 controls of European ancestry." (PMID 36707629, 2023). "In this study, we describe the geographic distribution of 66 different FANCM mutations identified in 44,803 female breast cancer cases from Europe, USA, Canada and Australia." (PMID 37444426, 2023). "But for one of the candidate genes, FANCM, the role in breast cancer predisposition appears more nuanced." (PMID 34584094, 2021). "This makes sense, since FANCM is a previously reported low-frequency gene associated with breast cancer." (PMID 34357098, 2021).
breast cancer (continued). "Historically, FANCM was implicated in breast cancer risk in 2013, based on exome sequencing of six multi-case breast cancer families and the resulting identification of the FANCM:c.5791 C >T PTV in an Italian proband." (PMID 34584094, 2021). "For example, ATM, a rare moderate-penetrance breast cancer susceptibility gene, is responsible for phosphorylation and chromatin recruitment in FANCM." (PMID 32300589, 2020). "On the other hand, the potential breast cancer susceptibility gene in the FA pathway, FANCM, is also needed for recruiting CtIP (C-terminal binding protein interacting protein) and MRN (MRE11-RAD50-NBS1) at the site of ICL, during the HR process." (PMID 32300589, 2020). "Germline protein truncating variants (PTVs) in the FANCM gene have been associated with a 2–4-fold increased breast cancer risk in case-control studies conducted in different European populations." (PMID 31991861, 2020). "In the last years, results from case-control studies have indicated that mono-allelic FANCM PTVs are breast cancer risk factors." (PMID 31991861, 2020). "A rare variant in FANCM was observed in cousins in two high‐risk pedigrees; has previously been reported as a breast cancer predisposition variant; has been reported, but not confirmed as associated with CRC risk, and has been analyzed further here." (PMID 33118316, 2020). "A rare stopgain variant in FANCM (rs144567652) that is recognized as a breast cancer predisposition variant, and that has previously been proposed, but not confirmed, as a CRC predisposition variant, is validated here as a risk factor for familial CRC." (PMID 33118316, 2020). "In this study we investigated the association of the three recurrent FANCM truncating variants p.Arg658*, p.Gln1701*, and p.Arg1931*, with breast cancer risk overall and by tumor subtype." (PMID 31700994, 2019). "In the Finnish population, FANCM:c.5101 C > T (p.Gln1701*, rs147021911) is relatively frequent and was reported to be associated with breast cancer with odds ratio (OR) of 1.86 with 95% confidence intervals (CIs) = 1.26–2.75." (PMID 31700994, 2019). "We analyzed the association of three FANCM truncating variants, p.Arg658*, p.Gln1701*, and p.Arg1931*, with breast cancer risk for each variant separately and using a burden analysis." (PMID 31700994, 2019). "FANCM, which encodes for a DNA translocase, has been proposed as a breast cancer predisposition gene, with greater effects for the ER-negative and triple-negative breast cancer (TNBC) subtypes." (PMID 31700994, 2019). "FANCM has been identified as a breast cancer susceptibility gene, and its deficiency is associated with breast cancer, especially triple-negative breast cancer." (PMID 30022024, 2018). "The authors focused on FANCM loss-of-function mutations and reported an OR of 2.44; 95% CI [1.08–5.59]; p = 0.02 for breast cancer cases diagnosed before the age of 51." (PMID 29351780, 2018). "Following the discovery of these “new breast cancer genes”, it has been suggested that RECQL and FANCM should be included on gene panel tests for breast cancer susceptibility." (PMID 29351780, 2018). "The study revealed the FANCM c.5791C>T mutation being more frequent among the studied breast cancer cases than in controls in the Finnish population." (PMID 28702895, 2017). "Another, yet more rare FANCM mutation, c.5791C>T (rs144567652, p.Arg1931*) in exon 22, has been identified with exome sequencing of breast cancer patients." (PMID 28702895, 2017). "The frequency of the FANCM c.5791C>T mutation was higher among breast cancer cases than in controls (OR 1.94, 95% CI 0.87–4.32, P = 0.11), with a statistically significant association with triple-negative breast cancer (OR 5.14, 95% CI 1.65–16.0, P = 0.005)." (PMID 28702895, 2017). "This is consistent with the effect of the majority of the known breast cancer-associated gene mutations, further supporting the impact of FANCM c.5791C>T on genomic instability and increased cancer risk." (PMID 28702895, 2017).
breast cancer (continued). "The FANCM c.5101C>T nonsense mutation was previously found to associate with breast cancer in the Finnish population, especially among triple-negative cases." (PMID 28702895, 2017). "The FANCM c.5293dupA and c.4025_4026delCT variants were genotyped among 862 familial breast cancer patients from the Helsinki area." (PMID 28702895, 2017). "The phenotypes associated to FANCM biallelic mutations thus far are cancer predisposition, in particular early-onset breast cancer in females, and chemosensitivity." (PMID 29231814, 2017). "Very recently two studies report that the phenotypes associated to FANCM biallelic mutations thus far are cancer predisposition, in particular early-onset breast cancer in females, and chemosensitivity." (PMID 29231814, 2017). "The current results on FANCM c.5791C>T, together with those of c.5101C>T, support a role for FANCM as a moderate-risk breast cancer susceptibility gene and further emphasize its connection with the triple-negative breast tumors." (PMID 28702895, 2017). "The genetic analysis identified a mutation in a gene called FANCM, which is involved in the cell’s repair response to DNA damage and has recently been linked to breast cancer." (PMID 29231814, 2017). "The FANCM c.5791C>T mutation was identified in altogether 28 breast cancer patients and eight controls among 4806 breast cancer patients and 2734 population controls from four different geographical areas of Finland (Helsinki, Tampere, Kuopio, and Oulu)." (PMID 28702895, 2017). "A recent study in a German population produced similar results, where the loss-of-function mutations in the FANCM gene were associated with both familial breast cancer and TNBC." (PMID 28702895, 2017). "A second study reported that the FANCM non‐sense mutation c.5791C>T, leading to exon 22 deletion and loss of DNA repair function, also confers a small increase in the familial breast cancer risk." (PMID 27037238, 2016). "One recent study reported a nonsense variant in FANCM (c.5101C>T) associated with a twofold increase in breast cancer susceptibility in the Finnish population." (PMID 27037238, 2016). "The absolute risk of breast cancer among FANCM LoF carriers is likely much lower than other intermediate breast cancer susceptibility genes, since ER-negative and triple negative BC constitute the minority of overall breast cancers and that is the main subtype with an increased risk." (PMID 40841357, 2025). "The FANCM gene has been suggested as a predisposition gene for breast cancer." (PMID 40832744, 2025). "However, biallelic FANCM variants are suggested to cause a FA‐like cancer predisposition syndrome characterized by early onset breast cancer, chemotherapy toxicity, and chromosome fragility." (PMID 40832744, 2025). "The breast cancer risk and functional effects of the truncating variants are considered to depend on their location within the FANCM gene, with N‐terminal loss of function (LoF) variants associated with a more detrimental effect than the C‐terminal LoF variants." (PMID 40832744, 2025). "Thus, despite the effect of FANCM heterozygosity on breast cancer predisposition remains unproven, it is important to detect breast cancer cases with biallelic FANCM variants to avoid treatments with excessive side effects." (PMID 40009290, 2025). "Our results support the definition from previous analyses of FANCM as a moderate-risk breast cancer gene and provide evidence that FANCM MVs could be low/moderate risk factors for ER-negative and TNBC subtypes." (PMID 36707629, 2023). "Association between FANCM missense variants (MVs) and breast cancer risk has been postulated." (PMID 36707629, 2023). "Finally, we considered the two studies published so far testing the association between FANCM MVs and breast cancer risk conducted using familial designs and excluding carriers of BRCA1 or BRCA2 pathogenic variants." (PMID 36707629, 2023).
breast cancer (continued). "While this supports the hypothesis that FANCM MVs are breast cancer risk factors, the ORs we found in this study are an overestimate of the risks these variants confer." (PMID 36707629, 2023). "FANCM deficiency is associated with a higher risk of breast cancer and liver cancer, and irreversible lesions are rapidly caused by FANCM deficiency on ALT cells, indicating that short-term inhibition of FANCM can effectively eliminate ALT tumours without secondary effects." (PMID 35205225, 2022). "Until recently, FANCM variants had only been reported in association with breast cancer." (PMID 36425062, 2022). "Based on these genetic and functional data, it is possible to speculate that the effects on breast cancer risk of the different FANCM PTVs might be due to the extent of protein truncation of the PTV." (PMID 34584094, 2021). "Could this explain the differences between studies investigating FANCM variants and their impact on breast cancer?" (PMID 34584094, 2021). "As FANCM protein is a large, multi-domain anchor that binds both DNA and other protein complexes at DNA damage sites, different effects may arise relating to breast cancer predisposition, depending upon the protein domains deleted." (PMID 34584094, 2021). "Conversely, the risk effects of FANCM:p.Gln1701* and p.Gly1906Alafs12* on these breast cancer subtypes are probably lower but may be amplified by additional variants acting as modifiers." (PMID 34584094, 2021). "Altogether, these data indicate that, while the association with risk for breast cancer was inconclusive, FANCM PTVs might be risk factors for familial breast cancer or for ER-negative and TNBC disease subtypes." (PMID 34584094, 2021). "Similarly to other genes such as BARD1, RAD51D, BRIP1, and RAD51C, FANCM is emerging as a breast cancer predisposing factor conferring a greater risk specifically for these breast cancer subtypes." (PMID 31991861, 2020). "The outcomes of functional assays testing the DNA repair efficiency in complemented human cells support the hypothesis that breast cancer risk may be greater for N-terminal than C-terminal FANCM truncating variants." (PMID 31700994, 2019). "In the BCAC dataset we assessed the breast cancer risk associated with the FANCM variants in a primary overall analysis and in a restricted analysis including only countries in which the variant carrier frequencies were higher than the median of the frequencies." (PMID 31700994, 2019). "Several FA genes (FANCD1/BRCA2, FANCN/PALB2, FANCJ/BRIP1, FANCO/RAD51C, and FANCS/BRCA1) are high- or moderate-risk breast or ovarian cancer susceptibility genes and previous studies have connected also heterozygous FANCM mutations with breast cancer predisposition." (PMID 28702895, 2017). "Also, the recently identified c.4025_4026delCT (p.Ser1342*) and c.5293dupA (p.Thr1765Asnfs*3) variants in the FANCM gene were studied among 862 familial breast cancer patients from the Helsinki area." (PMID 28702895, 2017). "Here, we have investigated the association of the FANCM c.5791C>T mutation with breast cancer risk in familial and unselected breast cancer cases among 4806 invasive breast cancer patients and 2734 healthy population controls from four different geographical areas of Finland." (PMID 28702895, 2017). "FANCM is a DNA-damage response gene whose heterozygous mutations predispose to breast cancer." (PMID 29231814, 2017). "In addition, we found a pathogenic FANCM variant (R1931*) which has been recently implicated in familial breast cancer risk." (PMID 28591191, 2017). "Mutations in the FANCM gene may cause a particular type of breast cancer known as ER-negative." (PMID 37444426, 2023). "In these studies, some individuals carrying biallelic nonsense mutations in FANCM were identified: a patient shows B-cell precursor lymphoblastic leukemia, two siblings developed squamous carcinomas in the mouth and neck and five cases are correlated with breast cancers." (PMID 32962238, 2020).
breast cancer (continued). "However, FANCM:p.Arg658* showed a higher heterozygote frequency in ER-negative breast cancer cases (0.093%) than in controls (0.035%) with a greater than two-fold increased breast cancer risk (OR = 2.44, 95% CI = 1.12–5.34, P = 0.034)." (PMID 31700994, 2019). "However, their identification may suggest a wider mutation spectrum of very rare mutations in the FANCM gene, potentially relating to subtype-specific breast cancer predisposition." (PMID 28702895, 2017). "Case 10 with early onset breast cancer (35 years) was identified as a compound heterozygote for FANCM c.5101C > T and c.5791C > T, and had triple-negative ductal tumor together with ductal/lobular carcinoma in situ and lymphovascular invasion." (PMID 40009290, 2025). "In the present, larger cohort, we report the spectrum and frequency of four common and 62 rare FANCM PTVs found in 274 carriers detected among 44,803 breast cancer cases." (PMID 37444426, 2023). "This discovery highlights a broader role for FANCM as a CRC risk gene and not only as a breast cancer risk gene." (PMID 36425062, 2022). "A second FANCM PTV, the c.5791C > T (p.Gly1906Alafs12*, rs144567652), which is annotated and hereafter referred to as p.Arg1931*, showed association with breast cancer risk in familial cases with OR = 3.93." (PMID 31991861, 2020). "As far as we know, this is the largest available collection of breast cancer probands carrying FANCM PTVs." (PMID 31991861, 2020). "Through a project call addressed to ENIGMA consortium collaborators, we collected data from European female breast cancer probands who were subjected to the sequencing of the FANCM coding region, resulting as carriers of a FANCM PTV." (PMID 31991861, 2020). "During the onset of carcinogenesis, shifted splicing of DNA repair genes has previously been documented in several cancer studies, such as BRCA1 and FANCM in breast cancer and ERCC1 in ovarian cancer." (PMID 31636653, 2019). "In order to estimate individual breast cancer risk for carriers of mutations in RECQL and FANCM, very large sample sizes and family based studies are required." (PMID 29351780, 2018). "FANCM and RECQL have recently been reported as breast cancer susceptibility genes and it has been suggested that they should be included on gene panel tests for breast cancer predisposition." (PMID 29351780, 2018). "A case-control screening of the coding region of FANCM was recently performed in 2047 familial breast cancer cases, 628 ovarian cancer cases and 2187 controls from Germany." (PMID 29351780, 2018). "Finally, a FANCM nonsense mutation c.5101C>T (p.Q1701X) has been identified as a susceptibility allele for triple-negative breast cancer in the Finnish population and was observed in 2.8% of unselected breast cancer patients and in 3.1% of breast cancer families." (PMID 28874143, 2017). "Here we have genotyped the CHEK2 mutations I157T and c.1100delC, the FANCM mutation p.Q1701X, the PALB2 mutation c.1592delT, the RAD51C mutations c.837+1G>A and c.93delG, and the RAD51D mutation c.576+1G>A in 68 male breast cancer patients." (PMID 28874143, 2017). "Other potential sources of DNA repair deficiency in breast cancer, also involving DSB repair processes, include germline mutations in DNA repair genes PALB2, FANCM, ATM, CHEK2 (and possibly also RAD51C) characterized as loss-of-function variants." (PMID 28679371, 2017). "Based on the results, FANCM c.5101C > T and c.5791C > T variants do not associate with breast cancer at heterozygous state, but the carrier tumors have a trend towards triple-negativity, which is in line with the existing literature." (PMID 40009290, 2025). "Interestingly, FANCM is a contradictory DDR gene, since its most common truncating variants, c.5101C > T and c.5791C > T, have only a minor effect on the overall breast cancer risk but associate with triple-negative subtype." (PMID 40009290, 2025).